KCNQ1OT1 (KCNQ1 opposite strand/antisense transcript 1)
Diseases named in the same sentence as KCNQ1OT1 in open-access papers (continued):
Sharing a sentence is not in itself a finding about the gene and the disease.
pneumonia (2 papers, 2021 to 2023). An acute, acute and chronic, or chronic inflammation focally or diffusely affecting the lung parenchyma, caused by an infection in one or both of the lungs (by bacteria, viruses, fungi, or mycoplasma.). "We aimed to explore the role of the lncRNA KCNQ1OT1 in pneumonia and its underlying mechanisms." (PMID 34301223, 2021). "However, little is currently known regarding the specific role and underlying mechanism of KCNQ1OT1 in pneumonia." (PMID 34301223, 2021). "Silencing of lncRNA KCNQ1OT1 alleviates lipopolysaccharide-induced lung injury by regulating the miR-370-3p/FOXM1 axis in childhood pneumonia." (PMID 37280583, 2023). "We offer the first evidence for the regulatory role of KCNQ1OT1 via regulation of the miR-370-3p/forkhead box protein M1 (FOXM1) axis in pneumonia." (PMID 34301223, 2021). "We confirmed that lncRNA KCNQ1OT1 directly interacts with miR-370-3p and reverse regulates the expression of miR-370-3p in LPS-induced pneumonia in vitro and in vivo." (PMID 34301223, 2021). "The results indicated that the relative expression of KCNQ1OT1 was notably elevated in the serum of patients with pneumonia compared to the serum of healthy individuals (P < 0.01)." (PMID 34301223, 2021). "In summary, lncRNA KCNQ1OT1 was up-regulated in the serum of patients with pneumonia and in LPS-treated WI-38 cells and mice." (PMID 34301223, 2021). "In line with the expression trend of previous studies, we also observed the up-regulation of KCNQ1OT1 in the serum of patients with pneumonia and LPS-treated WI-38 cells and mice compared with the controls." (PMID 34301223, 2021). "The regulatory role of the KCNQ1OT1/miR-370-3p/FOXM1 axis in pneumonia was further analysed in a mouse model of LPS-induced lung injury." (PMID 34301223, 2021). "In the current study, the role of lncRNA KCNQ1OT1 was explored in LPS-induced cellular and mouse models of pneumonia." (PMID 34301223, 2021). "Silencing of KCNQ1OT1 alleviates LPS-induced lung injury by regulating the miR-370-3p/FOXM1 axis in pneumonia." (PMID 34301223, 2021). "Our results further confirmed the key role of the KCNQ1OT1/miR-370-3p/FOXM1 axis in the progression of pneumonia, providing new ideas for its clinical treatment." (PMID 34301223, 2021). "Our findings may assist with understanding the function of KCNQ1OT1 in pneumonia and provide potential therapeutic strategies for pneumonia." (PMID 34301223, 2021). "KCNQ1OT1 may be a potential target for the treatment of pneumonia, showing promising prospects in clinical practice." (PMID 34301223, 2021). "Pneumonia may be diagnosed by measuring KCNQ1OT1 expression in the serum of patients." (PMID 34301223, 2021). "The expression of KCNQ1OT1 and FOXM1 was up-regulated, and miR-370-3p was down-regulated in the serum of children with pneumonia, LPS-treated WI-38 cells, and in lung tissues of LPS-treated mice." (PMID 34301223, 2021). "Therefore, we speculated that KCNQ1OT1 participates in the progression of pneumonia." (PMID 34301223, 2021). "The expression of KCNQ1OT1, FOXM1, and miR-370-3p was detected in the serum of 24 children with pneumonia and in 24 healthy controls." (PMID 34301223, 2021). "Nevertheless, the relationship between lncRNA KCNQ1OT1 and miR-370-3p has not yet been completely expounded in pneumonia." (PMID 34301223, 2021). "Taken together, we concluded that si-KCNQ1OT1 might serve as a competitive endogenous RNA to regulate the expression of FOXM1 by sponging miR-370-3p, thereby alleviating injury from pneumonia." (PMID 34301223, 2021).
retinoblastoma (2 papers, 2021). A malignant tumor that originates in the nuclear layer of the retina. "However, the expression and biological functions of KCNQ1OT1 in retinoblastoma (RB) are still unknown." (PMID 33345272, 2021).
transient neonatal diabetes mellitus (2 papers, 2015 to 2020). Transient neonatal diabetes mellitus (TNDM) is a genetically heterogeneous form of neonatal diabetes (NDM) characterized by hyperglycemia presenting in the neonatal period that remits during infancy but recurs in later life in most patients. "Genetic mutations underlying epimutations have been reported very infrequently in other imprinting disorders, including Russell–Silver Syndrome, transient neonatal diabetes mellitus and Beckwith–Wiedemann syndrome associated with KCNQ1OT1 (imprinting control region 2) hypomethylation." (PMID 25005734, 2015). "In 2005 for the first time there were reported two patients with MLID presented transient neonatal diabetes mellitus (TNDM) and hypomethylation of both iDMRs of KCNQ1OT1 gene and of PLAGL1, an antiapoptotic gene located at chromosome 6q24." (PMID 33101381, 2020).
acute promyelocytic leukemia (1 paper, 2021). An aggressive form of acute myeloid leukemia (AML), characterized by arrest of leukocyte differentiation at the promyelocyte stage, due to a specific chromosomal translocation t(15;17) in myeloid cells. "LncRNA KCNQ1OT1 is found to contribute to carcinogenesis, but its role in acute promyelocytic leukemia (APL) is unclear." (PMID 34404765, 2021).
Age-related cataract (1 paper, 2022). A type of cataract (opacification of the lens) that forms during the course of aging. "The finding revealed that down-regulation of lncRNA KCNQ1OT1 protected LECs from oxidative stress stimulated apoptosis via regulating the miR-124-3p/BCL2L11 pathway in age-related cataract." (PMID 35170373, 2022).
autoimmune disease (1 paper, 2022). A disorder resulting from loss of function or tissue destruction of an organ or multiple organs, arising from humoral or cellular immune responses of the individual to their own tissue constituents. "We selected NEAT1 and KCNQ1OT1 as the lncRNAs with the most interactions with microRNAs in autoimmune diseases and the Th17 differentiation pathway." (PMID 35266286, 2022).
breast tumors (1 paper, 2021). "Data from TCGA showed that compared to normal tissue, MIAT was up-regulated, while KCNQ1OT1, LOC100270804, and FLJ10038 were down-regulated in breast tumor tissues." (PMID 34209776, 2021).
celiac disease (1 paper, 2019). An autoimmune genetic disorder with an unknown pattern of inheritance that primarily affects the digestive tract. "Third, we corrected the observed methylation degree based on the estimated calibration curves in two specific target regions (KCNQ1OT1 and H19/IGF2) important for their BWS clinical diagnostic value and in three target genes that have been associated with susceptibility to celiac disease." (PMID 31049595, 2019).
endothelial dysfunction (1 paper, 2022). In vascular diseases, endothelial dysfunction is a systemic pathological state of the endothelium (the inner lining of blood vessels) and can be broadly defined as an imbalance between vasodilating and vasoconstricting substances produced by (or acting on) the endothelium. "KCNQ1OT1 could play an essential mediator role in endothelial cell physiologic development, and endothelial dysfunction could affect the pathogenesis of SSBP." (PMID 36235643, 2022).
epilepsy (1 paper, 2019). A brain disorder characterized by episodes of abnormally increased neuronal discharge resulting in transient episodes of sensory or motor neurological dysfunction, or psychic dysfunction. "Thus, our study indicated that KCNQ1OT1 may be a promising target to overcome drug resistance to AEDs in epilepsy." (PMID 31920517, 2019). "Collectively, our results suggested that KCNQ1OT1 contributes to AED resistance through the miR-138-5p/NF-κB/ABCB1 axis in HBMEC/PHT cells, and these results provide a promising therapeutic target for the treatment of medically intractable epilepsy." (PMID 31920517, 2019). "In summary, our study indicated that KCNQ1OT1 promotes drug resistance of AEDs in vitro through targeting the miR-138-5p/NF-κB/ABCB1 axis, providing a potential target for overcoming drug resistance in epilepsy." (PMID 31920517, 2019).
esophageal squamous cell carcinoma (1 paper, 2021). Esophageal squamous cell carcinoma (ESCC) is a type of esophageal carcinoma (EC) that can affect any part of the esophagus, but is usually located in the upper or middle third. "However, the biological function of KCNQ1OT1 in esophageal squamous cell carcinoma (ESCC) remains unclear." (PMID 33909822, 2021).
fibrosis (1 paper, 2021). the formation of excess fibrous connective tissue in an organ or tissue in a reparative or reactive process. "MALAT1 was found to be associated with inflammation and apoptosis processes, whereas Kcnq1ot1 association was identified with pyroptosis, cardiac fibrosis, and inflammation." (PMID 33639953, 2021).
gout (1 paper, 2025). A condition characterized by painful swelling of the joints, which is caused by deposition of urate crystals. "KCNQ1OT1 binds to miR-98-5p by adsorbing it, thereby competing with miR-98-5p for the binding sites of its target genes, relieving the inhibitory effect of miR-98-5p on its target genes, thus demonstrating the expression of gout-related target genes." (PMID 40606658, 2025).
hydrops (1 paper, 2010). "However, close inspection of individual profiles revealed that within the SCNT-hydrops group, there were individuals who showed aberrant hypo- or hypermethylation, particularly in the IGF2 exon 10 DMR, KCNQ1OT1, SNRPN and HAND1 regions." (PMID 20205951, 2010).
Kaposi's sarcoma (1 paper, 2021). A malignant neoplasm characterized by a vascular proliferation which usually contains blunt endothelial cells. "Of note, our bioinformatics analysis also demonstrated that Anril, Hotair, Malat1, Kcnq1ot1, and Meg3 regulate genes from the Kaposi sarcoma-associated herpes virus infection (KSHV) pathway." (PMID 33815273, 2021).
lipid metabolic disorders (1 paper, 2024). "For example, lipid metabolic disorders and inflammatory responses can be attenuated by KCNQ1OT1 knockdown or overexpression of miR-145-5p." (PMID 38457553, 2024).
male infertility (1 paper, 2023). The inability of the male to effect fertilization of an ovum after a specified period of unprotected intercourse. "We examined methylation of the ICRs of H19, MEST, KCNQ1OT1 and SNRPN, genes previously reported to be altered in male infertility and/or regions known to have roles in imprinting disorders." (PMID 36611168, 2023).
Myocardial fibrosis (1 paper, 2018). "Further, silencing Kcnq1ot1 alleviates myocardial dysfunction and attenuates myocardial fibrosis in STZ-induced C57BL/6 mice." (PMID 30250027, 2018).
Obesity (1 paper, 2022). Accumulation of substantial excess body fat. "Sal B exerted a chondroprotective effect by upregulating KCNQ1OT1, which indicates Sal B can used for a therapeutic agent in obesity-related OA." (PMID 35922815, 2022). "Thus, we reasonably speculate that there is a link between KCNQ1OT1 and Sal B-mediated protective effect in obesity-related OA." (PMID 35922815, 2022).
ocular toxoplasmosis (1 paper, 2019). Ocular toxoplasmosis is an infection in the eye caused by the parasite, Toxoplasm a gondii. "In our results—obtained in human retinal Müller cells, which have direct relevance to ocular toxoplasmosis—LINC01105, BANCR, MIR17HG, MIR155HG, lnc-SGK1, MEG3, KCNQ1OT1, NEAT1, NeST, and MALAT1 were the most dysregulated lncRNAs with known immunologic activities." (PMID 31547203, 2019).
omphalocele (1 paper, 2017). Omphalocele is an embryopathy classified in the group of abdominal celosomias and is characterized by a large hernia of the abdominal wall, centered on the umbilical cord, in which the protruding viscera are protected by a sac. "A well-defined (epi)genotype–phenotype correlation exists for omphalocele in BWS: it is caused by KCNQ1OT1:TSS-DMR loss of methylation in 86% of the cases, by CDKN1C mutation in 7%, and by UPD or H19/IGF2:IG-DMR gain of methylation in <10% of patients." (PMID 29047350, 2017). "Taken together, these findings suggest that KCNQ1OT1:TSS-DMR could be a susceptibility locus for the isolated omphalocele." (PMID 29047350, 2017). "Among the 19 cases with isolated omphalocele confirmed by follow-up, we observed a VUS (rs760463569) in CDKN1C in two cases (cases 16 and 20) and a rare variant of KCNQ1OT1:TSS-DMR in one case (case 19)." (PMID 29047350, 2017). "Thus, omphalocele can be considered one of the major and most frequent clinical manifestations of BWS in cases of KCNQ1OT1:TSS-DMR loss of methylation or CDKN1C mutations." (PMID 29047350, 2017). "We can surmise that alterations of methylation levels at H19/IGF2:IG-DMR and KCNQ1OT1:TSS-DMR are not primarily associated to omphalocele, in our cohort; conversely, sequence variants at KCNQ1OT1:TSS-DMR and CDKN1C could represent susceptibility factors for the onset of isolated omphalocele." (PMID 29047350, 2017).
osteomyelitis (1 paper, 2022). An acute or chronic inflammation of the bone and its structures due to infection with pyogenic bacteria. "Modulating KCNQ1OT1 expression may serve as a strategy to ameliorate osteomyelitis." (PMID 35226820, 2022).
ovarian disorder (1 paper, 2025). A disease involving the ovary. "Dysregulation of non-coding RNAs, including lncRNAs (e.g., NEAT1, KCNQ1OT1), circRNAs, and pseudogenes, further underscores the multifactorial nature of these ovarian disorders." (PMID 40725447, 2025).
Parkinson disease (1 paper, 2025). A progressive degenerative disorder of the central nervous system characterized by loss of dopamine producing neurons in the substantia nigra and the presence of Lewy bodies in the substantia nigra and locus coeruleus. "For example, LncRNA KCNQ1OT1 promotes NLRP3 inflammasome activation in Parkinson’s disease by regulating the pri-miR-186/mature miR-186/NLRP3 axis." (PMID 40652273, 2025).
pulmonary diseases (1 paper, 2021). "KCNQ1OT1 is a crucial modulator involved in the pathological processes of several pulmonary diseases." (PMID 34301223, 2021). "Up-regulation of lncRNA KCNQ1OT1 is intrinsically relevant to the pathogenesis of pulmonary diseases." (PMID 34301223, 2021).
renal fibrosis (1 paper, 2022). A final common manifestation of a wide variety of chronic kidney diseases characterized by glomerulosclerosis and tubulointerstitial fibrosis. "Hence, our current study was implemented to shed light on the potential role of KCNQ1OT1 in renal fibrosis progression and the underlying mechanism was illuminated by evaluating the relation between KCNQ1OT1 and miR-124-3p." (PMID 35443864, 2022). "In order to study on the possible target genes of KCNQ1OT1 involved in the occurrence and progression of renal fibrosis and assessed the KCNQ1OT1-associated miRNAs, we used bioinformatics analysis (Starbase, DIANA, and ENCORI) to search for genes that were directly regulated by KCNQ1OT1." (PMID 35443864, 2022). "Nevertheless, the pathological function of Long non-coding RNA KCNQ1OT1 (KCNQ1OT1) in the renal fibrosis remains obscure." (PMID 35443864, 2022). "The functions of KCNQ1OT1 on the progression of renal fibrosis were examined by CCK-8, EdU, dual-luciferase reporter, and immunofluorescence analyses." (PMID 35443864, 2022). "In the present study, we concentrated on the potential function of KCNQ1OT1 and further investigated its latent molecular mechanism in the renal fibrosis progression." (PMID 35443864, 2022). "To further investigate the role of KCNQ1OT1/miR-124-3p in the regulation of renal fibrosis, we artificially down-expressed miR-124-3p in HK-2 cells." (PMID 35443864, 2022). "Moreover, to investigate the relationship between KCNQ1OT1 and miR-124-3p in the progress of renal fibrosis, rescue experiment was performed." (PMID 35443864, 2022). "Based on the literature, we hypothesize that KCNQ1OT1 may play regulatory function in the progression of renal fibrosis." (PMID 35443864, 2022). "However, explorations about the exact role of KCNQ1OT1 in the progression of renal fibrosis are scanty." (PMID 35443864, 2022). "In the present study, we found that sh-KCNQ1OT1 obviously attenuated UUO-induced renal fibrosis." (PMID 35443864, 2022). "In conclusion, KCNQ1OT1 knockdown plays an anti-fibrotic effect through promotion of miR-124-3p expression in renal fibrosis, which provides a promising therapeutic target for the treatment of renal fibrosis." (PMID 35443864, 2022). "We investigated the role of KCNQ1OT1 in renal fibrosis using HK-2 cells in vitro." (PMID 35443864, 2022). "Hence, we speculated that KCNQ1OT1 effected renal fibrosis process through sponging the specific miRNA." (PMID 35443864, 2022). "In order to investigate the effects of KCNQ1OT1 on renal fibrosis in vitro, HK-2 cells were transfected with sh-KCNQ1OT1 and negative control, and qRT-PCR assay was performed to detect the transfected efficiency." (PMID 35443864, 2022). "However, to date, the roles of lncRNA KCNQ1OT1 in renal fibrosis progression was not illuminated." (PMID 35443864, 2022).
rhabdomyosarcoma (1 paper, 2024). A rare aggressive malignant mesenchymal neoplasm arising from skeletal muscle. "Interestingly, decreases of 0.6- and 0.7-fold in the expression level of KCNQ1 overlapping transcript 1 (Kcnq1ot1), and rhabdomyosarcoma 2 associated transcript (Rmst) were observed in MASH model mice." (PMID 39201613, 2024).
triple-negative breast carcinoma (1 paper, 2022). An invasive breast carcinoma which is negative for expression of estrogen receptor (ER), progesterone receptor (PR), and human epidermal growth factor receptor 2 (HER2). "Additionally, a recent study reported that KCNQ1OT1 participated in Yin Yang 1 (YY1)-mediated tumor-promoting effects on Triple-negative breast cancer (TNBC) through its interactions with DNMT1, in support of role of KCNQ1OT1 in TNBC." (PMID 36100884, 2022).
viral infection (1 paper, 2020). "The RNA–RNA interactions of downregulated KCNQ1OT1 with the mRNAs of these two genes may have implications on viral infection progression." (PMID 33224264, 2020).